IDH1 (isocitrate dehydrogenase (NADP(+)) 1)
Diseases named in the same sentence as IDH1 in open-access papers (continued):
Sharing a sentence is not in itself a finding about the gene and the disease.
chondrosarcoma (continued). "We show that p16/CDKN2A copy number variation occurs subsequent to the IDH1 mutation, and confirm that p16/CDKN2A copy number variation occurs in 75 % of high grade central chondrosarcomas, and not in low grade cartilaginous tumours." (PMID 25432631, 2015). "Although IDH1 inhibition completely inhibited colony forming activity in chondrosarcoma cells, this did not seem to be completely explained by the modest increase in apoptosis nor by cell cycle arrest." (PMID 26368816, 2015). "Although a fraction of skull base chondrosarcomas may be negative for IDH1/2 aberrations, it is also plausible that as a STM arising from a metastatic TGCT, this tumor is not driven by usual genetic mechanisms that underlie conventional chondrosarcomagenesis." (PMID 38236556, 2024). "Lastly, to determine whether depletion of mutant IDH sensitizes chondrosarcoma cells to specific compounds for potential combination therapies with mutant IDH inhibitors, we conducted a drug sensitivity analysis of mutant IDH1 KO cells and compared their responses to those of parental cells." (PMID 39684713, 2024). "A phase I trial demonstrated the promising activity of an IDH1 inhibitor, ivosidenib, particularly in conventional chondrosarcoma, where the progression-free survival was greater than in dedifferentiated chondrosarcoma, although the study was not powered to specifically compare those groups." (PMID 38254737, 2024). "Presence of a malignant TGCT with disseminated supradiaphragmatic lymphadenopathy, the unique immunophenotypic properties of the skull-based chondrosarcoma and lack of IDH1/2 aberrations with gain of 12p strongly support the diagnosis of STM chondrosarcoma arising from metastatic TGCT." (PMID 38236556, 2024). "Recently, Palubeckaite and colleagues have generated an alginate-based 3D cell culture model of chondrosarcoma to evaluate the treatment of chemotherapeutic drugs and target therapeutic agents including Sapanisertib (mTOR inhibitor) and AGI-519 (inhibitor of mutant IDH1)." (PMID 36622753, 2023). "However, this number was compounded by the exclusion of 41 patients, 28% of those recruited because of poor quality or inadequate DNA, in addition to which 20–30% of chondrosarcomas which do not harbour an IDH1/2 alteration." (PMID 34528398, 2021). "Moreover, direct inhibition of the IDH1 mutant enzyme does not change the tumorigenic properties of chondrosarcoma cell lines in vitro." (PMID 34070455, 2021). "Moreover, AGI-5198 significantly inhibited colony formation and migration of chondrosarcoma cells, without influence on IDH1-wt human normal chondrocytes, and induced an apoptotic cell death and G2/M cell-cycle arrest in human chondrosarcoma cells in vitro." (PMID 30857299, 2019). "Moreover, we previously demonstrated that mutant IDH1 is not essential for chondrosarcoma cell proliferation and survival, as its inhibition using AGI-5198 decreased levels of d-2-HG without affecting tumourigenic properties of chondrosarcoma cell lines." (PMID 28484589, 2017). "Thus, AGI-5198 appears to selectively inhibit longer-term tumor cell growth in IDH1-mutant chondrosarcoma cells while sparing non-malignant, IDH1 wild-type normal chondrocytes." (PMID 26368816, 2015). "Unlike “typical” cases of conventional head and neck chondrosarcoma, the STM chondrosarcoma showed loss of SMARCB1 expression, focal to diffuse immunostaining for epithelial markers, including EMA, CAM 5.2 and CK AE1/AE3, and 12p duplication with absence of IDH1/2 mutations." (PMID 38236556, 2024). "Analysis of our conventional chondrosarcomas (CHS) resulted in 56 of 98 samples not being predicted to a methylation class, which was partly accounted for by the DKFZ Classifier providing four different classes for these tumours based on IDH1/2 mutational status." (PMID 33949149, 2021).
chondrosarcoma (continued). "Additionally, long-term treatment of chondrosarcoma cell lines with the IDH1 mutant inhibitor AGI-5198 does not alter the DNA methylation phenotype, suggesting that the epigenetic alterations might have become independent of the IDH1 mutation." (PMID 31728625, 2020). "Although organic acids in mutant IDH1 and mutant IDH2 chondrosarcomas did not cluster separately from one another, they clustered separately from the non-mutant group." (PMID 33762012, 2021). "In a chondrosarcoma (HT1080) cell study, no increases in expression of fatty acid synthesis-related genes were observed in mutIDH1R132C relative to WT IDH1 cells." (PMID 35028610, 2021). "Here, we profiled over 69 metabolites in 17 patient-derived xenografts by targeted mass spectrometry to determine if metabolomic differences exist in mutant IDH1, mutant IDH2, and non-mutant chondrosarcomas." (PMID 33762012, 2021). "Alterations in IDH1/2 have been well described across several disease sites, including ICC, central nervous system tumors, chondrosarcomas, and acute non-lymphocytic leukemias." (PMID 34945742, 2021).
cholangiocarcinoma (168 papers, 2014 to 2026). A carcinoma that arises from the intrahepatic biliary tree (intrahepatic cholangiocarcinoma) or from the junction, or adjacent to the junction, of the right and left hepatic ducts (hilar cholangiocarcinoma). "We demonstrated for the first time EV proteome landscape changes caused by the IDH1 mutation and inhibitor treatment in intrahepatic cholangiocarcinoma, highlighting the utility of mDIA in EV-based biomarker discovery." (PMID 41519437, 2026). "Numerous IDH1 mutations were well-characterized in cholangiocarcinoma, especially in the intrahepatic type, occurring in approximately 13–15% of cases." (PMID 41153346, 2025). "The efficacy of this agent has been assessed in clinical trials for cholangiocarcinoma, a neoplasm that is distinguished by a relatively high frequency of IDH1 mutations." (PMID 41419593, 2025). "The most common gene alterations involving IDH1 are fusions, more frequent in intrahepatic cholangiocarcinoma, followed by amplification and activating mutations, found in extrahepatic tumors." (PMID 38846220, 2024). "Due to the statistically significant benefit of ivosidenib over placebo, the FDA granted approval for advanced cholangiocarcinoma with IDH1 mutation." (PMID 38730642, 2024). "The ClarIDHy phase III multicenter trial randomized 185 patients with IDH1-mutated cholangiocarcinoma (91.4% ICC) that had progressed on standard chemotherapy to either ivosidenib or placebo." (PMID 38398130, 2024). "Based on these results, in 2021, the FDA approved ivosidenib for adult patients with previously treated advanced IDH1-mutated cholangiocarcinoma." (PMID 39519290, 2024). "A multicentric phase III trial (ClarIDHy) investigated the role of Ivosidenib, a small-molecule inhibitor of mutated IDH1, in cholangiocarcinoma with IDH1-mutant and refractory to chemotherapy." (PMID 38203635, 2023). "Previous studies have shown that IDH-1/2 mutated cholangiocarcinoma displays increased evidence of DNA damage, making POLY-ADP Ribose Polymerase (PARP) inhibitors a potential therapeutic option." (PMID 38203714, 2023). "Cholangiocarcinomas share common driver genes including fusion transcripts, protein kinase A pathway, and IDH1/2 mutation, but also show heterogenous mutational signatures depending on their anatomic location and subtypes." (PMID 37108676, 2023). "To date, dozens of small molecules of IDH1/IDH2 inhibitors are under investigation, of which ivosidenib (AG-120) has been approved for the treatment of IDH1 mutated cholangiocarcinoma and acute myeloid leukaemia." (PMID 37980418, 2023). "In conclusion, this study indicated that IDH1 mutation in cholangiocarcinoma impairs tumor progression by sensitizing cells to erastin-induced ferroptosis." (PMID 35600114, 2022). "These resistance mechanisms suggest that IDH1-mutated cholangiocarcinomas remain dependent on (R)-2HG even after prolonged ivosidenib treatment." (PMID 36056177, 2022). "Pharmacological inhibition of mutant IDH1 offers a greatly needed therapeutic option for patients with IDH1-mutated cholangiocarcinoma, but, as with other targeted therapies, its effectiveness is limited by the development of acquired resistance." (PMID 36056177, 2022). "Mutations in isocitrate dehydrogenase 1 (IDH1) are presented in several human cancers including cholangiocarcinoma." (PMID 35600114, 2022). "The other indication of ivosidenib is for the treatment of locally advanced or metastatic, chemotherapy refractory cholangiocarcinoma with an IDH1 mutation based on data from the phase III study AG120‐C‐005 (ClarIDHy)." (PMID 36254250, 2022). "Current targeted inhibitors (AG120 and IDH305) of IDH1 mutation can selectively inhibit mutant IDH protein, which were used to further verify the effects of IDH1 mutation on erastin-induced ferroptosis in cholangiocarcinoma." (PMID 35600114, 2022). "It has also been shown that ivosidenib was effective in patients with IDH1 mutated cholangiocarcinoma." (PMID 35154988, 2022).
cholangiocarcinoma (continued). "Our previous study demonstrated that IDH1 mutations in cholangiocarcinoma impair tumor progression by inhibiting isocitric acid metabolism." (PMID 35600114, 2022). "In our previous study, IDH1 was identified as a high frequency mutated gene in patients with cholangiocarcinoma." (PMID 35600114, 2022). "The mutant IDH1 inhibitor ivosidenib improves outcomes for patients with IDH1-mutated cholangiocarcinoma, but resistance inevitably develops." (PMID 36056177, 2022). "Taken together, IDH1 mutation promotes erastin-induced tumor growth inhibition in cholangiocarcinoma." (PMID 35600114, 2022). "The in vivo experiment showed that IDH1 mutation in cholangiocarcinoma impairs tumor progression by sensitizing cells to erastin-induced ferroptosis." (PMID 35600114, 2022). "Ivosidenib is a small-molecular inhibitor of mutant IDH1 which has been shown to be mutated in various cancers such as colorectal cancer, prostate tumors, melanomas, leukemias, and cholangiocarcinoma." (PMID 35681621, 2022). "IDH1-mutated cholangiocarcinomas (CCAs) are an interesting group of neoplasia with particular behavior and therapeutic implications." (PMID 36335135, 2022). "The in vivo experiment showed that IDH1 mutation promotes erastin-induced tumor growth inhibition in cholangiocarcinoma." (PMID 35600114, 2022). "The results of the ClarIDHy trial led to the approval of ivosidenib for patients with previously-treated IDH1-mutated cholangiocarcinoma by the Food and Drug Administration (FDA)." (PMID 36056177, 2022). "Further studies are needed to define the effects of NRAS and other MAPK pathway mutations on primary and acquired resistance to ivosidenib in IDH1-mutated cholangiocarcinoma." (PMID 36056177, 2022). "One of the most common gene mutations in cholangiocarcinoma is affecting the IDH1/IDH2 gene (encoding isocitrate dehydrogenase isotypes), which is characteristic of the IHCC category." (PMID 35008396, 2022). "Due the high level of IDH1 mutations, which increase 5mC, a number of studies have attempted to reduce methylation in cholangiocarcinoma using inhibitors in cell lines." (PMID 34905094, 2022). "IDH1 mutation has been reported in various tumors especially Cholangiocarcinoma, while the IDH1_R132H is reported to be the most common mutation of IDH1." (PMID 35802554, 2022). "One case of conversion of IDH1 R132C to IDH1 R132F, and one case of isoform switching to mutant IDH2, have been reported in patients with IDH1-mutated cholangiocarcinoma who developed resistance to ivosidenib." (PMID 36056177, 2022). "It raises the possibility that IDH1 mutation in cholangiocarcinoma impairs tumor progression by inducing ferroptosis." (PMID 35600114, 2022). "Isocitrate dehydrogenase 1 (IDH1) mutation is reported as a gain-of-function mutation in up to 25% of cholangiocarcinoma, especially intrahepatic cholangiocarcinoma." (PMID 35802554, 2022). "This study indicated that IDH1 mutation in cholangiocarcinoma impairs tumor progression by sensitizing cells to erastin-induced ferroptosis." (PMID 35600114, 2022). "While the CCA-like histologically resembles HCC, molecularly, they look more like cholangiocarcinomas with similar patterns of DNA mutations (IDH1/2, BAP1), DNA damage repair mutational signatures, and transcriptional patterns." (PMID 36077818, 2022). "Cholangiocarcinoma RBE cell line was transfected with IDH1 R132C mutation plasmids and treated with erastin to induce ferroptosis, which were then microscopically photographed." (PMID 35600114, 2022). "This study indicated the important role of IDH1 mutation in the progression of ferroptosis in cholangiocarcinoma." (PMID 35600114, 2022). "Partly similar and more in-depth is this article reveals that IDH1 R132C mutation damages cholangiocarcinoma by inducing ferroptosis, and the evidence is the increase of lipid ROS level." (PMID 35600114, 2022).
cholangiocarcinoma (continued). "Taken together, IDH1 mutation in cholangiocarcinoma impairs tumor progression by sensitizing the cells to erastin-induced ferroptosis." (PMID 35600114, 2022). "IDH1 mutates in cholangiocarcinoma gain neomorphic enzymatic activity, whereby IDH1 is an important metabolic enzyme, and IDH1 can converts the NADPH-dependent reduction of α-KG to 2-hydroxyglutarate (2-HG)." (PMID 35802554, 2022). "One patient in this study with recurrence of previously resected cholangiocarcinoma was found to have an IDH1 R132L mutation and is under treatment with ivosidinib." (PMID 34439216, 2021). "The phase III ClarIDHy trial (NCT02989857) evaluated the IDH1 inhibitor ivosidenib in 185 previously treated patients with IDH1-mutated advanced cholangiocarcinoma." (PMID 33879235, 2021). "Subsequently, IDH1 inhibitor was also approved for newly diagnosed cases of AML, and currently the drug is being clinically evaluated for other cancers including cholangiocarcinoma with IDH1 mutation." (PMID 35996504, 2021). "The importance of the mutation is confirmed by the activity of IDH-inhibitors: inhibiting the mutant activity of either IDH1 or IDH2 shows anti-tumour activity in relapsed/refractory IDH1/2 mutated acute myeloid leukemia and cholangiocarcinoma patients." (PMID 33740099, 2021). "In the phase III trial ClarIDHy (NCT02989857), 185 patients (91% IHCC) with IDH1-mutated cholangiocarcinoma who had received 1 or 2 lines of prior therapy were treated with either ivosidenib or placebo." (PMID 34638259, 2021). "Phase 3 results are also positive for ivosidenib (AG120), an oral inhibitor of IDH1 in patients with IDH1-mutated cholangiocarcinoma who have failed one or two prior treatment lines." (PMID 33805461, 2021). "Frequent mutations of the IDH1 have also been identified in hormone receptor-positive (HR+) breast adenocarcinoma, thyroid cancer, cholangiocarcinoma (50–70%), and IDH2 (R172S) in benign giant cell tumors of the bone (80%)." (PMID 35996504, 2021). "In the present study, for the first time, IDH1 was identified as a high frequency mutated gene in patients with cholangiocarcinoma." (PMID 32373065, 2020). "In IDH1-mutated cholangiocarcinoma, reduced expression of H3K4me3 at the HNF4A promoter inhibits hepatocyte differentiation." (PMID 31728625, 2020). "The present study has identified IDH1 as a high frequency mutated gene in patients with cholangiocarcinoma." (PMID 32373065, 2020). "Specifically, the IDH1 inhibitor ivosidenib has been the first targeted agent to show a survival benefit in a randomized phase III trial of cholangiocarcinoma patients harboring IDH1 mutations." (PMID 33182517, 2020). "Of the cholangiocarcinomas, IDH1/2 mutations are found in intrahepatic cholangiocarcinomas (ICCs) and rarely, if ever, in perihilar or extrahepatic cholangiocarcinomas." (PMID 32978444, 2020). "The recent phase III ClarIDHy trial randomized 230 patients with advanced pretreated IDH-1 mutated cholangiocarcinoma to ivosidenib or a placebo (2:1)." (PMID 33182517, 2020). "The identification of cholangiocarcinoma patients with IDH1/IDH2 variants, which are mutually exclusive, may benefit from targeted therapies." (PMID 40075667, 2025). "A retrospective analysis of the ClarIDHy trial, which examined the efficacy of the IDH1 inhibitor ivosidenib in mutant IDH1 cholangiocarcinoma, showed that the clearance of IDH1 mutation, as assessed in plasma ctDNA in patients monitored over time, was associated with disease control." (PMID 38730713, 2024).